ENSG00000212134
Synonyms: LOC124900462
Gene: Small nucleolar RNA gene on chromosome 20 (31,376,319 to 31,376,446, forward strand). Ensembl gene ENSG00000212134.
Gene Ontology:
Biological process: RNA processing
Cellular component: nucleolus
Homologues: Paralogues in human: SNORA40B (93% identical), SNORA40 (91% identical), SNORA40C (88% identical).